CEP192 (centrosomal protein 192)
Description:
Required for mitotic centrosome maturation and bipolar spindle assembly. Appears to be a major regulator of pericentriolar material (PCM) recruitment, centrosome maturation, and centriole duplication. Centrosome-specific activating scaffold for AURKA and PLK1.
Synonyms: KIAA1569; FLJ10352; PPP1R62
Tractability: Small molecule: a structure with a bound ligand is known. PROTAC: UniProt records ubiquitination sites on it; ubiquitination databases record sites on it; its protein half-life has been measured.
Gene: Protein-coding gene on chromosome 18 (12,991,315 to 13,125,053, forward strand). Ensembl gene ENSG00000101639.
Subcellular location: Cytoplasm, cytoskeleton, microtubule organizing center, centrosome, centriole; Cytoplasm, cytoskeleton, microtubule organizing center, centrosome
Subcellular location (Human Protein Atlas): Cytosol; Basal body; Centrosome
Pathways (Reactome):
Cell Cycle: AURKA Activation by TPX2; Loss of Nlp from mitotic centrosomes; Loss of proteins required for interphase microtubule organization from the centrosome; Recruitment of NuMA to mitotic centrosomes; Recruitment of mitotic centrosome proteins and complexes; Regulation of PLK1 Activity at G2/M Transition
Organelle biogenesis and maintenance: Anchoring of the basal body to the plasma membrane
Gene Ontology:
Molecular function: phosphatase binding; protein binding
Biological process: centrosome-templated microtubule nucleation; mitotic spindle assembly; protein localization to centrosome; centriole replication; centrosome cycle; centrosome duplication
Cellular component: centriole; centrosome; ciliary basal body; procentriole; procentriole replication complex; cytoplasm; cytosol; pericentriolar material
Genetic constraint (gnomAD): Loss-of-function variants: 92 observed, 179.22 expected, observed/expected ratio (o/e) 0.51, 90% interval 0.43 to 0.61. The upper end of that interval is the gene's LOEUF score, 0.61, which puts it in group 2 of 6, group 1 being the genes least tolerant of losing a copy. Missense variants: 2,217 observed, 2,436.2 expected, observed/expected ratio (o/e) 0.91, 90% interval 0.88 to 0.94. Synonymous variants: 777 observed, 895.49 expected, observed/expected ratio (o/e) 0.87, 90% interval 0.82 to 0.92.
Homologues: Orthologues: chimpanzee CEP192 (99% identical), macaque CEP192 (94% identical), dog CEP192 (76% identical), mouse Cep192 (65% identical), rat Seh1l (65% identical), guinea pig CEP192 (63% identical), pig CEP192 (53% identical), tropical clawed frog cep192 (41% identical), zebrafish cep192 (36% identical).
Diseases named in the same sentence as CEP192 in open-access papers:
CEP192 is named in the same sentence as 28 diseases in open-access papers, as found by Europe PMC text mining. Sharing a sentence is not in itself a finding about the gene and the disease. The quoted sentences say what the papers report.
hepatocellular carcinoma (4 papers, 2022 to 2025). A malignant tumor that arises from hepatocytes. "Recently, CEP192 has been recognized as a new gene involved in the advancement of non-alcoholic fatty liver disease (NAFLD) to hepatocellular carcinoma (HCC) (Cai, Song & Yu, 2020)." (PMID 41048388, 2025). "did identify CEP192 as a novel prognostic marker in hepatocellular carcinoma based on increased expression with tumor stage and association with a high mortality and recurrence rate." (PMID 38606093, 2024). "• CEP192: Elevated levels in hepatocellular carcinoma.• Overexpression promotes cellular. proliferation and genomic instability." (PMID 38606093, 2024). "CHAF1A, CEP192, and AS3MT were reported to be associated with tumor progression involved with several tumors, such as hepatocellular carcinoma and lung cancer Further explorations are needed to investigate the biological mechanisms of these 6 shared genes on IS and obesity." (PMID 39734234, 2024).
cholangiocarcinoma (1 paper, 2022). A carcinoma that arises from the intrahepatic biliary tree (intrahepatic cholangiocarcinoma) or from the junction, or adjacent to the junction, of the right and left hepatic ducts (hilar cholangiocarcinoma). "In addition, CEP192 was increased not only in HCC but also in other types of cancer, including cholangiocarcinoma, esophageal carcinoma, head and neck squamous cell carcinoma, and lung adenocarcinoma." (PMID 36238304, 2022).
Cirrhosis (1 paper, 2022). A chronic disorder of the liver in which liver tissue becomes scarred and is partially replaced by regenerative nodules and fibrotic tissue resulting in loss of liver function. "In contrast, there was no significant relevance of CEP192 expression to precancerous lesions, such as fibrosis and cirrhosis." (PMID 36238304, 2022).
glioma (1 paper, 2025). A benign or malignant brain and spinal cord tumor that arises from glial cells (astrocytes, oligodendrocytes, ependymal cells). "Additionally, we identified five genes that not been implicated in glioma previously: CEP192 (18p11.21), D2HGDH (2q37.3) FAIM (3q22.3), HBEGF (5q13.3) and SLC8A1 (2p22.1)." (PMID 39565278, 2025).
liver cancer (1 paper, 2022). An epithelial or non-epithelial malignant neoplasm that arises from the liver. "Here, to explore the role and underlying mechanisms of CEP192 in HCC progression, we performed large-scale bioinformatic analyses of 2,151 samples from the TCGA, ICGC, and GEO liver cancer datasets." (PMID 36238304, 2022). "Subsequently, we identified 3 hepatic progenitor-like subpopulations with high CEP192 expression in liver cancer tissues, which exhibited robust proliferative potential and response to hypoxia, wounding, wound healing, toxic substance, and endoplasmic reticulum stress." (PMID 36238304, 2022). "Therefore, CEP192 may be a potential biomarker for cancer stem-like cells in liver cancer." (PMID 36238304, 2022). "Therefore, CEP192 may participate in HPC-driven immunosuppressive niche in liver cancer." (PMID 36238304, 2022). "Given the observed expression of CEP192 in HPC-like cells and PLVAP+ ECs, we hypothesized that CEP192 may participate in HPC-driven immunosuppressive niche in liver cancer." (PMID 36238304, 2022).
male infertility (1 paper, 2025). The inability of the male to effect fertilization of an ovum after a specified period of unprotected intercourse. "It has recently been found that mutations in human CEP192 can lead to MVA syndrome with tetraploidy and also a predisposition to male infertility." (PMID 40106572, 2025).
malignant melanoma (1 paper, 2016). "For example, ANLN and PRC1 were mutated in cells derived from a malignant melanoma, and RANBP2, TTK, PP2R1A, and CEP192 were mutated in cells from pancreatic cancers." (PMID 27144335, 2016).
microcephaly (1 paper, 2020). A congenital or acquired developmental disorder in which the circumference of the head is smaller than normal for the person's age and sex. "Similarly, pioneering work in C. elegans has revealed the importance of SPD-2 (CEP192 in humans) in centriole duplication and PCM maturation, but despite the clear association of other core centriole biogenesis components with microcephaly, CEP192 has not yet been implicated." (PMID 33178111, 2020).
non-alcoholic fatty liver disease (1 paper, 2022). "In recent years, CEP192 has been identified as a new gene in the progression of non-alcoholic fatty liver disease (NAFLD) to HCC." (PMID 36238304, 2022).
Obesity (1 paper, 2024). Accumulation of substantial excess body fat. "Several potential functional genes, including CHAF1A, CEP192, ULK4, CYP2D6, AS3MT, and WARS2, were identified as common genetic factors linking obesity and IS." (PMID 39734234, 2024). "The identification of CHAF1A, CEP192, ULK4, CYP2D6, AS3MT, and WARS2 as potential functional genes common to both obesity and IS enriched our understanding of their genetic interplay, potentially advanced our grasp of their pathogenesis and therapeutic targets." (PMID 39734234, 2024).
tumor (5 papers, 2022 to 2025). "Accordingly, CEP192 expression was closely associated with an immunosuppressive tumor microenvironment and low IPS, making it a potential predictor of response to ICIs." (PMID 36238304, 2022). "First, increased CEP192 expression in HCC was associated with tumor progression and predicted poor prognosis." (PMID 36238304, 2022). "CEP192 expression increased with tumor stage and was associated with poor clinicopathologic features, frequent recurrence, and higher mortality." (PMID 36238304, 2022). "Consequently, CEP192 expression was closely associated with an immunosuppressive tumor microenvironment and low immunophenoscores, making it a potential predictor of response to immune checkpoint inhibitors." (PMID 36238304, 2022). "PHDs altered the expression of Akt, centrosomal protein Cep192 and FOXO3a to regulate cell proliferation and viability, and showed their potential contribution to tumor development and metastasis via the changes of F-actin, NFκB or Sprouty2." (PMID 35281917, 2022). "Taken together, our results unravel a novel onco-immunological role of CEP192 in establishing the immunosuppressive tumor microenvironment and provide a novel biomarker, as well as a potential target for therapeutic intervention of HCC." (PMID 36238304, 2022). "Moreover, CEP192 was found to be upregulated in HCC tissues compared with that in the paired adjacent non-tumor tissues (TCGA, p < 0.001)." (PMID 36238304, 2022). "Also, immunohistochemical analysis showed an increase in CEP192 expression accompanied by a decrease in the number of infiltrating CD8+ T cells in tumor tissues compared with that in non-tumor tissues (–I)." (PMID 36238304, 2022). "Taken together, CEP192 might help establish an immunosuppressive microenvironment through interactions with Th2 cells in the HCC tumor niche." (PMID 36238304, 2022). "CEP192 was significantly increased in HCC tissues compared with that in adjacent non-tumor tissues based on seven HCC datasets, namely, GSE14520 (p < 0.001), GSE45267 (p < 0.001), GSE121248 (p < 0.001), GSE36376 (p < 0.001), GSE76427 (p < 0.001), GSE65372 (p < 0.001), and ICGC (p < 0.001)." (PMID 36238304, 2022). "Silencing CEP192 using siRNAs increased the proportion of cells in the G0/G1 phase and decreased the cell populations in the G2/M phase of the cell cycle, thereby preventing cell cycle progression and arresting tumor cell growth." (PMID 36238304, 2022). "Our study for the first time suggested that CEP192 was upregulated in HCC tissues and correlated significantly with tumor progression and adverse prognosis." (PMID 36238304, 2022). "We then examined the effect of CEP192 silencing on tumor cell proliferation and self-renewal using MTT and tumor colony formation assay." (PMID 36238304, 2022). "Notably, CEP192 was highly correlated with multiple tumor-associated cytokine ligand–receptor axes, including IL11–IL11RA, IL6–IL6R, and IL13–IL13RA1, which could promote interactions between hepatic progenitor-like cells, PLVAP+ endothelial cells, tumor-associated macrophages, and CD4+ T cells." (PMID 36238304, 2022). "Further research is needed to detect the tumor-infiltrating immune cell populations and cytokines in an orthotopic mouse HCC model with CEP192 inhibition, which will provide definitive evidence for the immunosuppressive role of CEP192 in HCC." (PMID 36238304, 2022). "Furthermore, 15 clinical tissues of HCC were collected to verify the protein expression levels of CEP192 using IHC analysis, and the results revealed a higher level of the CEP192 protein in HCC tissues than that in adjacent non-tumor tissues." (PMID 36238304, 2022). "Given the critical roles of CEP192 in the cell cycle, it is worth further exploring the impacts of CEP192 silencing on senescence and SASP factors, which may provide evidence for CEP192 as a therapeutic target to remodel the tumor microenvironment in HCC tissues." (PMID 36238304, 2022).
cancer (4 papers, 2019 to 2024). A tumor composed of atypical neoplastic, often pleomorphic cells that invade other tissues. "This concept was further supported by the positive correlation of CEP192 with characteristic onco-fetal genes, also known as cancer stem cell markers, including CD24, SOX9, CD47, and POU5F1 (OCT4)." (PMID 36238304, 2022). "Moreover, CEP192 was also discovered to be positively correlated with cancer stem cell markers including CD24, SOX9, CD47, and POU5F1 (OCT4)." (PMID 36238304, 2022). "Since Aurora-A is upregulated in certain cancer cell lines, which could influence the stoichiometry and function of the kinase:co-activator complexes, expression levels of these factors (i.e. Aurora-A, CEP192, TPX2, TACC3 and BORA) were determined across cell lines (Fig. EV1A)." (PMID 39327527, 2024). "The association between CEP192, NAB1 and CRC or other cancers, has not been described in previous studies." (PMID 33920880, 2021). "We show that while exosome-induced cancer cell motility requires neither centrosomes nor the MT network, it is critically dependent on CEP192, the CEP192 interacting kinase PLK4, and the Chromosomal Passenger Complex (CPC) protein Aurora Kinase B (AURKB)." (PMID 31142743, 2019).
hematological malignancies (1 paper, 2022). "CEP192 protein is indispensable for centrosome amplification, which has been extensively characterized in both hematological malignancies and solid tumors." (PMID 36238304, 2022).
infection (1 paper, 2017). The state of being infected such as from the introduction of a foreign agent such as serum, vaccine, antigenic substance or organism. "Interestingly, the integration of the functional genomics approach and GWAS data with the evolutionary genetics approach allowed us to identify reQTL for three genes, GFM1, CORO1C and CEP192, that likely have a major role against infection with M. leprae and/or T1R." (PMID 28793313, 2017).
CEP192 also shares sentences with these, for which no sentence is quoted: breast carcinoma (1 paper); calculus (1); colitis (1); esophageal carcinoma (1); fibrosis (1); glioblastoma (1); head and neck squamous cell carcinoma (1); invasive ductal carcinoma (1); lung adenocarcinoma (1); lung carcinoma (1); oral diseases (1); pancreatic cancers (1); periodontal diseases (1); sarcopenia (1).